NLRP3 (NLR family pyrin domain containing 3)
Diseases named in the same sentence as NLRP3 in open-access papers (continued):
Sharing a sentence is not in itself a finding about the gene and the disease.
colitis (continued). "Mice with NLRP3, ASC, or caspase-1 gene knockout are more susceptible to DSS-induced colitis, which is a result of reduced IL-18, a downstream component of the NLRP3 inflammasome." (PMID 37370025, 2023). "Apigenin (API) is a flavone (4,5,7-trihydroxyflavone) that is ubiquitously distributed in plants and has shown the ability to prevent DSS-induced colitis via regulating CASP1’s activity to inhibit the activation of the NLRP3 inflammasome in the colon." (PMID 37833958, 2023). "Taken together, SIT did ameliorate experimental colitis by inhibiting the NLRP3/Caspase-1/GSDMD-dependent pyroptosis pathway." (PMID 37954856, 2023). "NLRP3 can be activated by NF-κB as a first step in pathway activation, both of which regulate the balance between mucosal homeostasis and inflammation in colitis." (PMID 37284442, 2023). "Although previous studies have shown that NLRP3 has a protective effect on CRC, and Nlrp3−/− mice showed an increase in colitis and CRC development induced by DSS and AOM/DSS, recent studies seem to support the promoting effect of NLRP3 on CRC more." (PMID 37833958, 2023). "Administration of andrographolide to mice with DSS-induced colitis enhanced mitophagy in peritoneal macrophages, thereby inhibiting the NLRP3 inflammasome and subsequently ameliorating colitis." (PMID 37152076, 2023). "As PKR is controlling the activity of the inflammasomes and because NLRP3 has been shown to be important in colitis, we treated mice with the inhibitor CP456773 to assess the involvement of this sensor in the response to DSS." (PMID 36875104, 2023). "These components play a role in the NLRP3 inflammasome activation, which drives intestinal inflammation in colitis by consequent production of IL-1β and IL-18." (PMID 37513865, 2023). "A previous study has indicated that TRIM31 is the suppressor of NLRP3 inflammasome in sulfate-induced colitis." (PMID 36597090, 2023). "hucMSC-derived exosomes attenuate colitis by modulating macrophage pyroptosis via the miR–378a–5p–NLRP3 axis." (PMID 37238692, 2023). "In colitis-associated colorectal cancer (CAC), many studies found that the expression level of components of inflammasome such as NLRP3 decreased in the CAC mouse model." (PMID 37198617, 2023). "In accordance, DMF also alleviates dextran sulfate sodium-induced colitis, and sulforaphane protects from acute pancreatitis by controlling oxidative stress and the NLRP3 inflammasome through the transcription factor Nrf2." (PMID 37891937, 2023). "NLRP3 is required for chlorogenic acid amelioration of colitis, whereas knockdown of NLRP3 undermined the reversed effects of chlorogenic acid." (PMID 37813835, 2023). "The major fatty acid in royal jelly, 10-hydroxy-2-decenoic acid, improves the effects of DSS-induced colitis by mediating the NLRP3 inflammasome-mediated pyroptosis pathway and increasing intestinal barrier function." (PMID 37761139, 2023). "The NLRP3 inflammasome has been recognized as a potential therapeutic target of intestinal inflammation in the DSS colitis model." (PMID 37970386, 2023). "For instance, sanguinarine relieved DSS-induced experimental colitis by blocking the NLRP3 pathway and improving intestinal microbial disorders." (PMID 37446938, 2023). "TRIM31 has been reported to attenuate the activation of NLRP3 inflammasome in sulfate-induced colitis." (PMID 36597090, 2023). "Another small molecule inhibitor, andrographolide, slows down the development of colitis-associated colon cancer (CAC) in mice by mediating mitochondrial phagocytosis and inhibiting NLRP3 inflammasome activation in macrophages." (PMID 37497237, 2023). "Norisoboldine stimulates Treg differentiation and suppresses the NLRP3 inflammasome to alleviate the symptoms of colitis." (PMID 37179416, 2023). "OLT1177 (Dapansutrile), developed by Olatec in 2012, was the first specific NLRP3 inhibitor to successfully pass phase II (Clinical Trials Identifier: NCT01636141) in patients with colitis." (PMID 37891577, 2023).
colitis (continued). "In a colitis-based study in mice, evodiamine inhibited the inflammatory response by inhibiting NF-κB and NLRP3 inflammasomes, as well as enhancing autophagy and altering intestinal flora structure." (PMID 38054830, 2023). "A series of research showed that mice deficient in NLRP3 signaling components, including NLRP3, ASC and CASP1, were more likely to develop DSS-induced colitis." (PMID 37833958, 2023). "In the study of dextran sulfate-induced colitis in mice, evodiamine can inhibit the inflammatory response by inhibiting the expression levels of NF-κB and NLRP3, and can also upregulate the number of autophagosomes, thereby enhancing autophagy." (PMID 38054830, 2023). "Studies based on this model have shown that foxtail millet peptides produced by protein hydrolysis can alleviate DSS-induced colitis in mice by inhibiting NLRP3 inflammatory vesicle formation and Th17 cell differentiation." (PMID 38140314, 2023). "Of note, NLRP1 has been linked to inflammation in a mouse model of dextran sulfate sodium salt-induced colitis; increased cytoplasmic sodium concentrations activate NLRP3; and both NLRP3 and NLRC4 are hyperosmotic stress sensors." (PMID 37573430, 2023). "In the present study, we demonstrated an important activation of the NLRP3 complex following DNBS-induced colitis; however, Ulva pertusa treatments significantly decreased NLRP3, ASC, and Caspase-1 expressions, lessening NLRP3 inflammasome activity." (PMID 37233492, 2023). "Inhibit mtROS production and mtDNA oxidation to reduce NLRP3 inflammasome activation and alleviate colitis." (PMID 37533869, 2023). "The regulatory modulation of Nrf2 and NLRP3 inflammasome signaling leads to a superior anti-colitis effect." (PMID 37359553, 2023). "Research has shown that inhibition of p38 plays a protective role in many inflammatory disease models, including Parkinson’s disease, acute lung injury, colitis, and diabetic nephropathy, by regulating the activation of NLRP3 inflammasome." (PMID 36615880, 2023). "Immunohistochemistry was used to detect the expression of NLRP3 in colonic tissues of mice with DSS-induced colitis." (PMID 36762118, 2023). "Recent studies have shown the protective role of autophagy in NLRP3 inflammasome activation and amelioration of intestinal inflammation in murine colitis models." (PMID 36937852, 2023). "H2S was also reported to protect against dextran sulfate sodium-induced colitis or paraquat-induced acute liver injury by inhibiting NLRP3 inflammasome." (PMID 35910846, 2022). "Animal studies provided a chain of evidence in support of a key role for NLRP3 inflammasome in colitis." (PMID 35722277, 2022). "For instance, mice deficient in NLRP3 (Nlrp3-/-) have reduced inflammation in two IBD model systems (DSS and TNBS colitis)." (PMID 35185922, 2022). "NLRP3 inhibition was associated with reduced colitis severity and histological damage of colonic mucosa, supporting that PGA exerts an anti-inflammatory effect by suppressing NLRP3 activity through PPAR-α receptor involvement." (PMID 36009057, 2022). "Another bacterium, Roseburia, can decrease serum levels of proinflammatory cytokines and inhibit the activation of the nucleotide-binding oligomerization segment-like receptor family 3 (NLRP3) inflammasome in murine colitis." (PMID 36590590, 2022). "Mice treated with MCC950, a specific NLRP3 inhibitor, experienced resolution of acute or chronic colitis by inhibiting ASC oligomerization, caspase-1 dependent activation of IL-1β and IL-18, and reducing pro-inflammatory cytokines." (PMID 36199683, 2022). "Overall, our data suggest that WT161 alleviated colonic inflammation in DSS-induced colitis mice as an effective inhibitor of the NLRP3 inflammasome." (PMID 35330829, 2022). "Based on these studies, we suspect that the HDAC6 inhibitor WT161 can inhibit the activation of NLRP3 inflammasome and alleviate colitis in DSS-treated mice." (PMID 35330829, 2022).
colitis (continued). "Polysaccharide from Scutellaria baicalensis Georgi can improve colitis by inhibiting the NF-κB signaling pathway and activation of NLRP3 inflammasome." (PMID 35186102, 2022). "Studies have shown that the inhibition of NLRP3 inflammasome depends on the blockade of ERα in colitis." (PMID 35694250, 2022). "In this study, we found that the HDAC6 inhibitor WT161 exerts a protective effect in a DSS-induced colitis murine model and blocks NLRP3 inflammasome activation, as IL-1β release and ASC oligomerization were inhibited in the WT161-treated group." (PMID 35330829, 2022). "In a dextran sulfate sodium-induced murine colitis model, acupuncture relieved colitis symptoms by suppressing pro-inflammatory NLRP3/IL-1β, and promoting both the antioxidant Nrf2/HO-1 and the M1 to M2 transition." (PMID 36712435, 2022). "Studies have also found that intraperitoneal injection of formononetin can slow DSS-induced colitis by inhibiting NLRP3 inflammasomes." (PMID 35265068, 2022). "In a DSS-induced colitis model, NLRP3 (−/−) mice were shown to release less IL-1β, a central factor in the pathogenesis of IBD, and NLRP3 (−/−) mice were less likely to exhibit colitis than wild-type controls." (PMID 35677444, 2022). "Kynurenine, an endogenous metabolite of tryptophan, can endogenously exacerbate colitis by regulating the expression of intestinal NLRP3 inflammasomes." (PMID 36522791, 2022). "It was also indicated that curcumin alleviated DSS−induced colitis via inhibiting NLRP3 inflammasome activation and IL−1β production." (PMID 36290717, 2022). "In a dextran sulfate sodium (DSS)-induced colitis mouse model, miR-378 carried by hucMSC exosomes attenuated colitis by regulating macrophage pyroptosis and inhibiting NLRP3 inflammasome activation." (PMID 35884901, 2022). "In this study, we have shown that WT161, an inhibitor of HDAC6, exerts a protective role in a colitis model, blocks NLRP3 inflammasome activation, disrupts ASC speck formation, and decreases the expression of NLRP3." (PMID 35330829, 2022). "Recent reports suggested that NLRP3 inflammasome augments colitis via affection of pyroptosis, a new type of proinflammatory programmed cell death, which has many differences from apoptosis and necrosis." (PMID 35631426, 2022). "It was also found that mice genetically deficient in miR-223 display markedly exacerbated experimental colitis, as indicated by increased immune infiltration (neutrophils and monocytes), hyperactivated NLRP3, and IL-1β release." (PMID 36389791, 2022). "Our data showed that knockout or blockade of GPR84 significantly reduced IL-1β level in both colitis mice and M1 macrophages, suggesting the possible involvement of NLRP3 inflammasome." (PMID 34912006, 2022). "In this study, we found that WT161 ameliorated DSS-induced colitis by targeting the NLRP3 inflammasome, expanding its potential application in inflammatory diseases." (PMID 35330829, 2022). "There were some reports about the potential involvement of the NLRP3 inflammasome in intestinal epithelial cells after DSS−induced colitis." (PMID 36290717, 2022). "In conclusion, our study demonstrated that BUR alleviated DSS−induced colitis by improving intestinal barrier function, reducing apoptosis, and decreasing inflammation through the NLRP3 inflammasome inactivation." (PMID 36290717, 2022). "The researchers found that metformin/MCC950 attenuated DSS-induced colitis by inhibiting NLRP3 inflammasome via autophagy-mediated interactions between heat shock protein 90 and NLRP3." (PMID 36199683, 2022). "Pterostilbene derivatives have been revealed to improve experimental colitis by suppressing NLRP3-induced pyroptosis." (PMID 36160717, 2022). "The suppression of colitis by MSPNPs was further investigated by assessing the expression levels of NLRP3 inflammasome and caspase-1." (PMID 35745756, 2022).
colitis (continued). "A recent study has shown that cardamonin can inhibit the NLRP3 inflammasome activation and thus attenuate experimental colitis induced by both DSS and TNBS." (PMID 36090968, 2022). "On the other hand, NLRP3 inflammasome has been reported to play important roles in mediating colitis." (PMID 35712724, 2022). "They confirmed that Rev-Erbα regulates experimental colitis through its repressive action on the NF-κB/Nlrp3 axis." (PMID 35814267, 2022). "Excessive NLRP3 activation, which can be caused by knockdown of V-set and immunoglobulin domain-containing 4 (VSIG4), protects mice from DSS-induced colitis." (PMID 35677444, 2022). "In mice with chronic DSS-induced colitis, activation of the NACHT, LRR, and pyrin domain containing protein 3 (NLRP3) inflammasome in the meninges was proposed and linked to an increased infiltration of gut-derived T cells." (PMID 36232412, 2022). "A recent study has demonstrated that effectively suppressing NLRP3-induced pyroptosis can improve experimental colitis." (PMID 36160717, 2022). "Our previous study found that DHEA prevents NLRP3 inflammasome activation in the intestinal epithelium and inhibits colitis in mice." (PMID 35440074, 2022). "This is consistent with previous studies showing that activation of CB2 receptors ameliorates DSS-induced colitis by enhancing the inhibition of NLRP3 inflammasome activation in macrophages." (PMID 35401205, 2022). "Soybean isoflavones can alleviate DSS-induced colitis by inhibiting the ERα pathway and downregulating the subsequent activation of the NLRP3 inflammasome." (PMID 35694250, 2022). "MitA significantly inhibited SP1 and p-SP1 and ameliorated inflammation, while OA inhibited NLRP3 inflammasome and ameliorated colitis through promoting TGR5." (PMID 35712724, 2022). "For example, our previous study found that the natural products andrographolide, asiatic acid, and the synthetic compounds Fc11a-2 and AI44 inhibited NLRP3 inflammasome activation and thus prevented colitis and LPS-induced sepsis in mice." (PMID 36379253, 2022). "For example, a study claims that DSS potentiates NLRP3 inflammasome activation by regulating the KCa3.1 potassium channel in a mouse model of colitis." (PMID 36311726, 2022). "Previous reports on blockade of NLRP3 with this specific NLRP3 inhibitor effectively limited the induction of DSS colitis in mice, and inhibits NF-κB, IL-1β, caspase-1 and MPO activity." (PMID 35693797, 2022). "In a previous study, astragalus polysaccharide (APS) was found to alleviate colitis in mice by inhibiting NLRP3 inflammasome." (PMID 35409050, 2022). "In conclusion, in UC patients with specific genetic abnormalities and in several experimental models of colitis, excessive activation of NLRP3 inflammasome augments colonic inflammation." (PMID 36199683, 2022). "The beneficial effects of SBLF on colitis are mainly derived from its anti-inflammatory and anti-NLRP3 inflammasome effects." (PMID 36552376, 2022). "Bauer and colleagues reported that NLRP3 contributed to inflammatory bowel disease in DSS−triggered colitis and was detrimental for intestinal epithelial barrier−maintenance." (PMID 36290717, 2022). "Consistently, it has been demonstrated to exert an anti-inflammatory activity in a murine model of colitis, by specifically repressing NF-κB and Nlrp3 expression, thereby downregulating Nlrp3 inflammasome activity." (PMID 35136018, 2022). "When colitis was induced by dextran sulphate sodium (DSS), NLRP3−/− and IL18−/− mice were more susceptible to tumorigenesis." (PMID 35877745, 2022). "For instance, mice with Nlrp3, Asc, or Caspase-1 deficiency have been found to exhibit more severe experimental (DSS-induced) colitis and decreased intestinal epithelial integrity in some studies." (PMID 35185922, 2022).
colitis (continued). "An in vivo study showed that the anti-colitic effect of polysaccharide, extracted from Scutellaria baicalensis Georgi, on AA-induced colitis was found through the suppressing NF-κB signaling and the NLRP3 inflammasome." (PMID 36235004, 2022). "To investigate the in vivo inflammatory bowel disease inhibition potential of MLE, we tested the effect of MLE on a mouse model of DSS-induced colitis, characterized by significant NLRP3 inflammasome activation in colon tissue." (PMID 35967819, 2022). "Dihydroartemisinin prevented colitis through inhibition of the activation of the NLRP3 inflammasome, and NF-κB and MAPK signaling." (PMID 36120344, 2022). "Here we show that rCT-NAMPT served as an effective novel candidate therapeutic for colitis by modulating the NLRP3 inflammasome-mediated immune signaling system through negative regulation of signals 1 and 2 in response to NLRP3-inflammasome activation." (PMID 36552583, 2022). "In different mouse models (DSS, Oxazolone, and TNBS models) NLRP3 has been shown to protect epithelial integrity, regulate intestinal homeostasis, and attenuate experimental colitis." (PMID 35677444, 2022). "Baicalein can alleviate colitis severity induced by TNBS by inhibiting the activation of NLRP3 inflammasome and production of IL-1β in the colon." (PMID 36090968, 2022). "Previousfindings indicate that NLRP3, ASC, and caspase-1 expression aresignificantly upregulated in colitis; inhibition of the NLRP3 inflammasomepathway effectively reduces the severity of colitis." (PMID 39076616, 2022). "In vivo studies investigating DSS-induced colitis in Nlrp3-/- mice reported contrasting results on the severity of inflammation-related parameters compared to WT mice." (PMID 35911682, 2022). "Increasing evidence indicates that the activation of the NF-κB pathway and the NLRP3 inflammasome is widely involved in different diseases, such as colitis, diabetes, and COVID-19 infection-induced pneumonia in the peripheral tissue." (PMID 35721113, 2022). "BAFF blockade treatment has protective effects in colitis, probably related to the inhibition NF-κB signaling pathways and also the NLRP3 inflammasome." (PMID 35320937, 2022). "Sinapic acid has shown antioxidant and anti-inflammatory properties, as well as a modulating activity against the NLRP3 inflammasome complex in mouse models with chemically induced colitis." (PMID 35276849, 2022). "It should be noted that another compound extracted from AM, Astagalus Polysaccharide (AP), also showed anti-inflammatory effects and anti-colitis role via regulating the NLRP3 inflammasome." (PMID 36090968, 2022). "Exos derived from human umbilical cord MSCs are believed to release miRNA 378a-5p to macrophages, potentially targeting NLRP3 to attenuate colitis." (PMID 36160717, 2022). "A recent study has shown that Amuc_2109, an enzyme secreted by A. muciniphila, also attenuated DSS-induced colitis in mice, increasing the expression of TJs and reducing the expression of the NLRP3 inflammasome." (PMID 35874661, 2022). "Recently, we demonstrated that Litsea cubeba leaves ameliorate colitis in DSS-treated mice by inhibiting the NLRP3 inflammasome." (PMID 36552376, 2022). "Neutralizing BAFF can ameliorate colitis by reducing inflammation, inhibiting NF-κB and NLRP3 signaling pathways." (PMID 35320937, 2022). "Many studies have revealed that NLRP3 affects several inflammatory disorders to a large extent including colitis." (PMID 33505807, 2021). "Both aggravation as well as amelioration of colitis have been shown in patients and mice with various reasons of NLRP3 hyperactivation." (PMID 34344313, 2021). "In the present study, we investigated possible contributions of the NLRP3 inflammasome to exacerbation of neurological dysfunction by DSS-induced colitis in aging mice." (PMID 34229722, 2021).